MAGEC2 (MAGE family member C2)
Description:
Proposed to enhance ubiquitin ligase activity of RING-type zinc finger-containing E3 ubiquitin-protein ligases. Proposed to act through recruitment and/or stabilization of the Ubl-conjugating enzymes (E2) at the E3:substrate complex.
Synonyms: CT10; HCA587; MAGEE1; MAGE-C2
Tractability: PROTAC: ubiquitination databases record sites on it.
Gene: Protein-coding gene on chromosome X (142,202,342 to 142,205,290, reverse strand). Ensembl gene ENSG00000046774.
Subcellular location: Cytoplasm; Nucleus
Subcellular location (Human Protein Atlas): Nucleoplasm; Cytosol
Gene Ontology:
Molecular function: protein binding; ubiquitin protein ligase binding
Biological process: positive regulation of ubiquitin-protein transferase activity; protein catabolic process; negative regulation of transcription by RNA polymerase II
Cellular component: cytosol; nucleoplasm; nucleus; cytoplasm
Homologues: Orthologues: chimpanzee MAGEC2 (95% identical), macaque MAGEC2 (90% identical), mouse Magea13 (30% identical), rat Magea13 (30% identical), zebrafish ndnl2 (20% identical), Drosophila melanogaster MAGE (15% identical). Paralogues in human: MAGEC1 (58% identical), MAGEC3 (46% identical), MAGEA10 (44% identical), MAGEB18 (38% identical), MAGEA11 (37% identical), MAGEB17 (37% identical), MAGEB4 (37% identical), MAGEA9 (36% identical), MAGEA9B (36% identical), MAGEA1 (36% identical), MAGEA8 (36% identical), MAGEB10 (35% identical), and 25 more.